MMP2 (matrix metallopeptidase 2)
Diseases named in the same sentence as MMP2 in open-access papers (continued):
Sharing a sentence is not in itself a finding about the gene and the disease.
tumor (continued). "Importantly, this indicates that these stromal cells have only a modest capacity for self-activation of their own MMP2 and require a trans-activation of this protease by the MT1-MMP expressed by the nearby tumor cells." (PMID 33740019, 2021). "We found a downregulation of IFN-β in tumor tissue compared to control and a negative Pearson correlation with MMP-2 (− 0.501)." (PMID 33846436, 2021). "While APRIL, BAFF, IL8 and MMP2 did not modulate with tumor stage, they were inversely related to the immune infiltrate level and CD163 tissue expression." (PMID 33846436, 2021). "All neoplasms expressed MMP-2, MMP-9, MMP-14 and TIMP-1 independent of the infection state but displayed a variable distribution and intensity as demonstrated by immunohistochemistry." (PMID 33808256, 2021). "For example, MMP2 and MMP9 were possible tumor markers for breast cancer patients." (PMID 35069702, 2021). "For example, MMP-9 and MMP-2 cleave TGF-b, promoting tumor invasion, and angiogenesis." (PMID 34446834, 2021). "One possibility for this phenotype is that other DC subsets or APCs substitute for cDC1 activity in the absence of MMP2 and promote tumor control." (PMID 34032639, 2021). "In cancer cells, which overexpress MMP-2, CTX was shown to be a promising tumour-targeting ligand." (PMID 34067049, 2021). "The data presented that PCNA, MMP2 and MMP9 were all strikingly downregulated in the sh-hsa_circ_0004712 experimental group compared to the sh-NC control group, while the level of C-caspase 3 was opposite to them, suggesting that tumor growth was inhibited." (PMID 34507595, 2021). "Furthermore, overexpression of MMP‐2 and MMP‐9 is closely correlated with tumor invasion and migration." (PMID 34531985, 2021). "Interestingly, MMP2 and MMP9 are largely involved with hypoxia, tumor progression, and immune evasion." (PMID 34359789, 2021). "Among matrix MMPs family, MMP‐2 and MMP‐9 are the two important enzymes involved in the EMT process, which specifically degrade gelatin, collagen, elastin, and fibronectin, thereby inducing invasion and metastasis of tumor cells." (PMID 34977870, 2021). "Matrix metalloproteinase-2 (MMP-2) and matrix metalloproteinase-9 (MMP-9) are enzymes related to degradation of the extracellular matrix and play an important role in the metastasis of tumours to distant tissues and organs." (PMID 34222329, 2021). "In addition, MMP‐2, MMP‐7 and MMP‐9, the target genes of Wnt/β‐catenin signaling, function to degrade extracellular matrix and basement membrane to promote tumor cell metastasis." (PMID 34165914, 2021). "Moreover, we have investigated the stromal score, immune score, and tumor purity of five subtypes, along with the estimate score of MMP1, MMP2, MMP9, MMP12, MMP13 in five subtypes of BRCA." (PMID 35069702, 2021). "Moreover, TNF is a proinflammatory cytokine secreted by macrophages, T-lymphocytes and mastocytes, inducing an overexpression of MMP-2, MMP-3, MMP-7 and MMP-9 in the tumor microenvironment, contributing to the invasive capacity of malignant cells." (PMID 34204372, 2021). "In this case, a mouse MMP-2 knockout model exhibited reduced tumor burden, suggesting expression within the tumor is not necessarily essential for MMP-2." (PMID 33808504, 2021). "In addition, the activities of MMP2 and MMP9 were largely declined in tumor tissues in the sh-hsa_circ_0004712 group." (PMID 34507595, 2021). "Moreover, the morphological changes and expression of Bcl-2 family proteins, MMP-2, and PCNA in tumor tissues were regulated by CR treatment in vivo, and were consistent with the in vitro results." (PMID 33946527, 2021). "Moreover, the authors found that the MMP-2/TIMP-2 ratio is higher in CRC tissue compared with healthy tissue, and decreases with tumor stage, depth of invasion and lymph node metastasis." (PMID 34071492, 2021).
tumor (continued). "As exhibited by immunohistochemistry, the positive rates of SALL4, MMP-2, MMP-9, and PCNA proteins were decreased in tumor tissues of mice treated with exosomes, and these trends were further facilitated in the tumor tissues of mice treated with miR-15a agomir-exos." (PMID 34455417, 2021). "Based on our results, we can suggest greater utility of serum TIMP-1 compared with MMP-9, MMP-2, and TIMP-2 in the diagnosis of CRC, particularly in the assessment of the tumor stage, survival of cancer patients, resectability of the tumor, and in the differentiation between CA and CRC." (PMID 34071492, 2021). "In tumor tissue, we found that the expression of MMP-2 was not statistically significant between the two groups, while the expression of MMP-9 in the LF group was higher than that in the control group." (PMID 34819565, 2021). "Previous reports indicated that MMP-2 and MMP-9 were related to tumor invasion and metastasis." (PMID 34685504, 2021). "ECs can influence ECM remodeling either by the expression of MMPs such as MMP2 and MMP9 or by the release of cytokines like CCL2, IL-8 and CXCL16, which act in a paracrine manner by upregulating the expression of MMPs in other cell types, such as tumor cells." (PMID 34073394, 2021). "In addition, results from western blotting indicated the expression of MMP-2 and MMP-9 proteins, which are great contributors to tumor cell migration, was significantly downregulated after the induction of RA in these two CC cell lines." (PMID 33621954, 2021). "The digestion of abalone intestine with an in vitro gastrointestinal (GI) digestion system resulted in the identification of two peptides with anti-MMP-2 and anti-MMP-9 activity in human fibrosarcoma cells (HT1080 cells), namely abalone oligopeptide (AOP) and abalone anti-tumor peptide (AATP)." (PMID 33498927, 2021). "Histology of HGSC tumor revealed positivity for Pan-CK, markers of Mullerian epithelium (PAX8, WT1) and Ki67, as well as the markers of aggressiveness, matrix metallopeptidase (MMP) 9 and MMP2." (PMID 33530497, 2021). "The absence of lymphocytes reduced the overt tumor growth of Mmp2-OE cells and reconstitution with CD4+ T cells (OTII+) partially rescued the phenotype." (PMID 34032639, 2021). "MMP2, MMP9 and MMP13 are prominent enzymes that promote tumor cell invasion and migration and regulate the progress of epithelial-to-mesenchymal transition (EMT), which is a transformation process of the epithelial cells to the mesenchymal cells and can promote cancer metastasis." (PMID 34820358, 2021). "Likewise, increased expression of IL1A (log2 fold change = −4.15) and TGFA (log2 fold change = −2.28) was observed in the HCC tumor cells leading to increased expression of TME-derived MMP9 and MMP2, respectively." (PMID 33995488, 2021). "Interestingly, a high variability of MMP2 and MMP9 activity levels was recorded between different patients, suggesting their possible role in tumor progression." (PMID 34830271, 2021). "In addition, the expressions of MMP2 and MMP9 in TNBC cells has also been further detected, which were considered to have a high correlation in tumor migration and invasion events." (PMID 34858165, 2021). "Lycopene supplementation (1, 20 mg/kg BW; 2 times per week for 12 weeks) in nude mice injected with SK-Hep-1 cells managed to significantly reduce MMP-2, VEGF, PCNA, MMP-9, suppress tumor metastasis, mean number of tumors, tumor cross-sectional area while increase nm23-H1." (PMID 34202203, 2021).
tumor (continued). "The transition of TAMs into M2 state releases an abundant amount of transforming growth factor TGF-β, epithelial growth factor (EGF), matrix metalloproteinase MMP-2 and MMP-9, and IL-10, thus promoting tumor angiogenesis and invasion, as well as immune-suppressed microenvironment." (PMID 34439380, 2021). "Besides, the down-regulation of matrix metalloprotein 2 (MMP2) and MMP9 also reduced the rate of tumor metastasis." (PMID 34051801, 2021). "Members of the MMP family, including MMP-2 and MMP-9, are overexpressed in many cancer types and can promote the destruction of extracellular matrix and play a critical role in tumor invasion and metastasis." (PMID 34078185, 2021). "Additionally, FN1 was shown to induce MMP2 and MMP9 expression during the malignant progression of human cancers in previous studies, which was conducive to tumor migration, invasion, angiogenesis, and intravasation." (PMID 34758823, 2021). "The cleavage peptide was then expected to be specifically attacked by MMP-2/9 setting free the nona-arginine–DOX conjugate only at the tumor site, and further triggering its cellular uptake and subsequent targeted drug release." (PMID 33805680, 2021). "Western blot showed that the protein expression levels of FSTL3, Vimentin, N-cadherin, MMP2 and MMP-9 in the mice tumor tissue in the sh-LBX2-AS1 experimental group were decreased, indicating that FSTL3 expression was increased at protein level and EMT was promoted." (PMID 34858481, 2021). "In addition, Cyr61 promotes vasculogenic mimicry (VM) formation, thereby promoting tumor growth and metastasis through a αVβ5/FAK/HIF‐1α/STAT3/MMP2 signaling cascade." (PMID 33999512, 2021). "In addition, the coordinating action of MMP-2 and MMP-9 have been identified as contributing factors to ECM degeneration, photoaging, and tumor progression." (PMID 33925954, 2021). "MMP-2 (gelatinase-A) and MMP-9 (gelatinase-B) are the markers of tumor invasion." (PMID 33233701, 2020). "Taken together, we show for the first time that Porf-2 is capable of suppressing tumor cell migration via its GAP domain and the downregulation of MMP-2/9, suggesting that targeting Porf-2 could be a promising therapeutic strategy for nervous system tumors." (PMID 32676454, 2020). "This MDM2 DNA could be transferred to preadipocytes (P-a), a major and ubiquitous cellular component of the DDLPS tumor microenvironment (TME), with subsequent P-a production of matrix metalloproteinase 2 (MMP2), a critical component in the metastatic cascade." (PMID 32258243, 2020). "There was a statistically significant difference in the immunoexpression of HIF-1α, MMP-2, VEGF/VEGFA, and VEGFR-2 proteins between the parenchyma of tumour cells and the stroma of tumour cells, where the parenchyma cells of AME showed a higher immunoexpression compared to the stromal cells." (PMID 33067558, 2020). "In addition, during tumor invasion and metastasis, MMP-2, MMP-7, and MMP-9, the target genes of Wnt/β-catenin signaling, function to degrade the ECM and basement membrane so that tumor cells can detach, invade, and metastasize." (PMID 33542902, 2020). "MMP2 and VEGFA are both recognized as the molecular biomarkers of tumor angiogenesis." (PMID 32600379, 2020). "Moreover, gavage administration of SG inhibited the protein level of MMP2 and MMP9 in the tumor tissues of the xenograft model." (PMID 32508048, 2020). "It has been found that the fragments released by MMP-2 and MMP-9 cleavage of SCUBE3 can bind to transforming growth factor-b (TGF-b) type II receptors, thus activating TGF-b signal transduction to promote tumor progression." (PMID 32322168, 2020). "In addition, both MMP2 and TGF-β1 proteins as well as IL6 and IL8, whose secretion levels were high in hADSCs-IL2, are important participants in EMT of tumor cells." (PMID 32560387, 2020). "MMP2 and MM9 are closely related to the invasion and metastasis of several types of tumor cells." (PMID 32164618, 2020).
tumor (continued). "Shikonin could downregulate MMP2 which can cleave or degrade ECM and promot tumor invasion and metastasis, but when decreases galectin-1 though shikonin fail to do it." (PMID 31892852, 2020). "MDSCs also support tumor angiogenesis by producing angiogenic factors such as VEGF, platelet-derived growth factor (PDGF), transforming growth factor beta, CXCL8, and matrix metalloproteinases (MMPs) such as MMP-2 and MMP-9." (PMID 31991604, 2020). "Moreover, MMP2 and MMP9, as proteolytic enzymes, are involved in the degradation of extracellular matrices, which play a crucial role in tumor invasion and metastasis." (PMID 33024414, 2020). "Furthermore, ETV5 has been reported to directly influence the transcription of MMP2 and TIMP to modify tumor growth." (PMID 33099574, 2020). "For example, CAFs rely on the activation of HIF-1 to secrete carbonic anhydrase (CAIX), which raises the acidity of extracellular matrix; CAFs secrete MMP-2/9, therefore inducing the epithelial-mesenchymal transition (EMT) in tumour cells and enhancing the migration ability of tumour cells." (PMID 32066485, 2020). "In many studies, inhibition of MMP-2 and MMP-9 decreased tumor angiogenesis." (PMID 32351671, 2020). "Besides, MMP2 and MMP9 can degrade collagen in the basement membrane of blood vessels, which is involved in angiogenesis, tumor invasion and migration." (PMID 33098235, 2020). "Some of these genes, which interfere with tumor cell growth/differentiation/migration/invasion (such as MYC, MET, PROM1, and PTK2), induce hypoxia (such as ARNT2, HIF3A, TGB2, MMP2, and POSTN) and genes regulating transcription via acetylation were downregulated upon pembrolizumab treatment." (PMID 32616706, 2020). "Our study found that Rab11a increased invasion ability and positively regulated MMP2, a potent protease that could degrade ECM and promotes tumor cell invasion, suggesting Rab11a promotes invasion through MMP2." (PMID 33178272, 2020). "MMP2 and MMP9, the major proteolytic enzymes contributed to ECM degradation, are involved in the process of releasing vascular endothelial growth factor (VEGF), promoting tumor cell migration and invasion." (PMID 32970612, 2020). "MMP-2 and its inhibitors TIMP-1 and -2, also function in tumor invasion and metastasis." (PMID 32960785, 2020). "Promelittin is not toxic to normal tissue but can be activated by MMP‐2 that is enriched in tumor microenvironment, leading to release of free melittin, which lyses and kills adjacent tumor cells." (PMID 32154067, 2020). "Intriguingly, in many solid tumors, MMPs are produced by tumor stromal cells, rather than by tumor cells, including tumor-associated interstitial collagenase (MMP-1), stromelysin-1 (MMP-3), stromelysin-3 (MMP-11), and gelatinase A (MMP-2)." (PMID 32948029, 2020). "Moreover, increased expression levels of MMP2 and MMP9 helped to enhance tumor cell invasion ability." (PMID 32269963, 2020). "The findings in some of these studies have additionally suggested that ZKSCAN3 could modulate several molecules known to play a key role in tumorigenesis and/or tumor progression, such as cyclin D1/D2, EGF, IGF-2, integrin-β4, MMP2/MMP9, NF-κB, and VEGF." (PMID 32824199, 2020). "In addition, eHsp90α can also stabilize and activate matrix metalloproteinase-2 (MMP-2) to degrade extracellular matrix (ECM), which is essential for tumor cells to invade out from the primary tumor and form metastases." (PMID 31936169, 2020). "It should be noted that also other proteases, which are released by macrophages, including MMP2 and MMP9, might play a role in tumor-induced damages of the sciatic nerve." (PMID 32013137, 2020). "Several studies have demonstrated that TAMs might produce some angiogenesis-related enzymes, including MMP-2 and MMP-9, which mediate ECM degradation and increase the vascular invasion of tumor cells." (PMID 32972437, 2020).
tumor (continued). "In addition, curcumin administration increased caspase-3 activity and reduced MMP-2 and MMP-9 activity within the tumor tissue, indicating that curcumin can promote apoptosis and inhibit MMP secretion at the location of the tumor to prevent cancer progression." (PMID 33182828, 2020). "Moreover, MMP‐2 and MMP‐9 expressions, markers for tumor invasiveness, were also increased in A549‐IR cells." (PMID 32328272, 2020). "Additionally, it has been observed that NE induced overexpression of cytokeratin (CK), matrix-metalloproteinase-2 (MMP-2) and -9 (MMP-9) that was paralleled by EMT effects and correlated to higher mobility and invasive behaviors of tumor cells." (PMID 33457324, 2020). "Expression of matrix metalloproteases 2, 9 and 14 (MMP-2, MMP-9, MMP-14), tissue inhibitors of metalloprotease 1 and 2 (TIMP-1, TIMP-2) and vascular endothelial growth factor A (VEGF-A) is involved in tumor invasion and metastasis via extracellular matrix degradation and angiogenesis." (PMID 32669083, 2020). "Upon histological evaluation, the tumor population and the levels of active STAT3, Ki-67, Bcl-xL, and pro-MMP-2 were elevated, and that of active caspase-3 was decreased in vehicle-treated control mice, indicating that the proliferation and growth of tumor cells were active in this group." (PMID 32183406, 2020). "However, compared to Porf-2 overexpression, overexpression of MMP-2 exhibited smaller wound area and showed similar genotype as control, suggesting that MMP-2 blocked the effect of Porf-2 on tumor cell migration." (PMID 32676454, 2020). "MMP-1, MMP-2, MMP-3, and MMP-7 are able to control the growth of tumor cells by mechanisms such as the release of precursors of growth factors that are attached to the cell membrane, modulating the bioavailability of growth factors and regulating cell proliferation signals." (PMID 33419373, 2020). "The nanostructure swelled in a weakly acidic tumor niche due to the protonation of the functional 3-diethylaminopropyl isothiocyanate (DEAP), and released the loaded NLG919 due to the cleavage of the peptide substrate by matrix metalloproteinase-2 (MMP-2)." (PMID 32528926, 2020). "As our expectation, the protein expressions of Jagged2, Notch, MMP-2/MMP-9 and PI3K/AKT/mTOR signaling were significantly reduced by Mel treatment and further significantly reduced by silenced Notch/JAG2 in the harvested tumor mass." (PMID 32792862, 2020). "Doxorubicin and palladium were loaded into a triglyceride monostearate carrier, which could be degraded by matrix metalloproteinase 2 (MMP2), an enzyme that is overexpressed in the tumor microenvironment." (PMID 33260534, 2020). "Moreover, CAFs produce matrix metalloproteases 1 and 2 (MMP1 and MMP2) and FGF2, shaping the ECM structure and promoting tumor cell survival, respectively." (PMID 33167307, 2020). "In addition, numerous studies mentioned that MMP‐2 and MMP‐9, which are both regulated by the ERK/MAPK pathway, participate in cancer progression, including tumour growth, angiogenesis, cell invasion and migration." (PMID 32893977, 2020). "MMP2 and TGF-β1 both play an important role in EMT of tumor cells." (PMID 32560387, 2020). "Once the clusters of nanoparticles accumulated inside the tumor due to the EPR effect, upregulated content of MMP-2 in the tumor microenvironment destructed the clusters to release small nanoparticles (∼5 nm), which deeply penetrated into the hypoxia region of the tumor." (PMID 33330618, 2020). "By correcting the MMP2 activation signal with the probe concentration signal, MMP2 fluorescence activation is displayed in the tumor independent of delivery concentration." (PMID 32349205, 2020). "MMP-14 mediates tumour invasion and angiogenesis and PEDF may reduce tumour cell metastatic potential by negatively regulating MMP-14, and subsequent MMP-2 activation in various cancer types, including BC." (PMID 33238558, 2020).